CXCL12 (C-X-C motif chemokine ligand 12)
Diseases named in the same sentence as CXCL12 in open-access papers (continued):
Sharing a sentence is not in itself a finding about the gene and the disease.
breast carcinoma (continued). "In addition, it is indicated that CXCL12 expression was substantially associated with aneuploidy and microsatellite instability (MSI) in breast cancers." (PMID 37564657, 2023). "Summarily, this study revealed the immunological implication and prognostic significance of CXCL12 in breast cancer, and that its related biomarkers might provide us with a novel research direction for the diagnosis and treatment of breast cancer." (PMID 37564657, 2023). "The mixture of CXCL4 and CXCL12 or the obligate CXCL4•CXCL12 heterodimer inhibited CXCL12-induced migration of MDA-MB-231 breast cancer cells, increased cytoplasmic Ca2+ release and activated downstream signaling of CXCR4 but not CXCR3, highlighting its role in limiting cancer progression." (PMID 37446102, 2023). "In addition to regulating immune checkpoint molecules, circ_002172 inhibited cytotoxic T cell (CTL) infiltration and promoted breast cancer development by upregulating C-X-C motif chemokine ligand 12 (CXCL12) expression via miR-296-5p." (PMID 36797245, 2023). "Therefore, we investigated the role of curcumin in ameliorating this complicated microenvironment of breast cancer by modulating the CXCL12/CXCR4 axis." (PMID 38004606, 2023). "Besides, we found that CXCL12 was highly expressed in breast cancer tissues from patients with stage I, compared to those with stage II, III and IV disease." (PMID 37564657, 2023). "Furthermore, a systematical meta-analysis study has revealed that breast cancer patients with high CXCL12 expression harbor an OS advantage." (PMID 37564657, 2023). "Besides, we performed immunohistochemistry (IHC) analysis to validate that breast cancer patients with higher expression of CXCL12 possess preferred outcomes." (PMID 37564657, 2023). "Regarding the pleiotropic effects of DPP-4 inhibitors on cancer biology, we have previously shown that DPP-4 suppression accelerates breast cancer metastasis by inducing EMT through C-X-C motif chemokine 12 (CXCL12)/C-X-C receptor 4 (CXCR4)-mediated mTOR activation." (PMID 37760498, 2023). "Moreover, the authors discovered that the expression of CXCR4 gene is overexpressed compared to breast cancer lung metastasis cells, with CXCR4 interacting with CXCL12 to induce breast cancer cell migration." (PMID 35884845, 2022). "Among these, CXCL12, ESR1, IGF1, and FOS were associated with breast cancer survival." (PMID 35463082, 2022). "Thus, breast cancer cells with high levels of CXCR4 have a marked tendency to migrate to the sites rich in CXCL12, including bone marrow." (PMID 35236304, 2022). "Indeed, organs with the highest levels of CXCL12 expression (lymph nodes, lung, liver, and bone marrow) are the most common sites of metastasis for breast cancer cells." (PMID 36229490, 2022). "Since dimeric PKM2 is known to drive the glycolytic metabolism of glucose and accumulation of metabolites in glycolysis and the pentose phosphate pathway, our signaling data provide one potential mechanism for CXCL12-stimulated shifts in the metabolism of breast cancer cells." (PMID 35681470, 2022). "As one of the most widely studied chemokines, CXCL12 has been reported in both haematological and solid tumours, including acute myeloid leukaemia, lymphoma, cervical cancer, lung cancer, colorectal cancer, and breast cancer." (PMID 36312898, 2022). "In addition, doxycycline‐induced ENTREP expression suppressed the chemotaxis of mouse breast cancer 4T1‐Luc cells toward CXCL12." (PMID 34927784, 2022). "Here, we show that cancer cells of human pancreatic ductal adenocarcinoma (PDA), colorectal cancer, and breast cancer are coated with transglutaminase-2 (TGM2)–dependent covalent CXCL12–keratin-19 (KRT19) heterodimers that are organized as filamentous networks." (PMID 35046049, 2022). "CXCL12 is of significant importance in the immune escape of breast cancer cells." (PMID 35203510, 2022).
breast carcinoma (continued). "Moreover, CXCL12 hyper-methylation was discovered in multiple tumors, like stomach carcinoma, mammary carcinoma, colon carcinoma, pulmonary carcinoma, and prostate cancer, which suggested a possible role of CXCL12 in carcinogenesis." (PMID 36211359, 2022). "Similarly, upregulation of CXCR4 and downregulation of CXCL12 were observed in primary breast cancers." (PMID 35770088, 2022). "Although our study identified possible pathological roles for IGF1, ESR1, and CXCL12 in breast cancer and a potential synergistic effect of formononetin with immune checkpoint inhibitors in breast cancer immunotherapy, the limitation of this study is that it is only a data analysis-based prediction." (PMID 35463082, 2022). "In conclusion, our findings predict that IGF1, ESR1, and CXCL12 may be effective targets of formononetin as a therapeutic for breast cancer." (PMID 35463082, 2022). "Thus, all detectable CXCL12 that was associated with cancer cells in six consecutive surgical samples of human PDA, CRC, and breast cancer, respectively, is covalently bound to KRT19." (PMID 35046049, 2022). "Higher CXCL12 protein expression indicated a better disease-free survival and overall survival in breast cancer patients, and had a positive relation with positive estrogen receptor (ER) status, negative human epidermal growth factor receptor (Her)-2 status, and small tumor size." (PMID 35079936, 2022). "The authors quantified breast cancer cell transmigration in response to different shear stress levels (2.5 and 10 dyn/cm2; corresponding to 5 and 20 μl/min flow rate respectively) as well as a chemotactic gradient (100 ng/ml of the chemokine CXCL12)." (PMID 33777909, 2021). "The CXCL12/CXCR4 axis is said to have a critical role in breast cancer metastasis." (PMID 34066014, 2021). "It is demonstrated that breast cancer EVs show strong liver tropism rather than kidney tropism on both the microfluidic and animal models and a CXCL12 mediated chemokine gradient that is unique to the liver PMN is responsible for the breast cancer EV organotropism." (PMID 33777909, 2021). "The secretion of CXCL12 by breast cancer cells can enhance invasion, recruit macrophages, and increase microvessel density, which may also be mediated by tumor-associated macrophages and contributes to altered tumor architecture." (PMID 33773539, 2021). "CXCL12 might constitute one of the systemic bone-derived factors that would directly promote breast cancer cell proliferation and metastasis." (PMID 34858421, 2021). "The breast cancer cell lines are attracted through chemokines CXCL16 and CXCL12 by fibroblasts that are associated with BCBM and therefore, blocking receptor-ligand interaction of CXCR6-CXCL16/CXCR4-CXCL12, which may be preventive therapy for BCBM." (PMID 34944840, 2021). "Comparison of TNC expression with CD8 and CXCL12 expression in breast cancer patients." (PMID 33988305, 2021). "There were 12 unique analyses with significantly high expression of CXCL11 in breast cancer and 12 unique analyses in colon cancer, and 16 unique analyses with significantly low expression of CXCL12 in breast cancer, and 3 unique analyses with significantly low expression in pancreatic cancer." (PMID 34439306, 2021). "Most importantly, treatment of the invasive mammary tumour cells with the combination of CXCL12 and CCL19 at suboptimal concentrations, elicited a very strong synergistic response in inhibiting cAMP, paralleling results obtained in cells from advanced primary human breast cancer." (PMID 34685420, 2021). "In addition, tumor cell-derived angiopoietin-like protein 2 (Angptl2) induces CXCR4 and activates CXCL12/CXCR4 signaling in breast cancer cells, leading to bone metastasis." (PMID 33096815, 2020). "Thus, CXCL12/CXCR4 blockade boosts the efficacy of immune checkpoint blockers in preclinical models of breast cancer." (PMID 33096815, 2020).
breast carcinoma (continued). "High CXCL12 expression was associated with reduced overall survival in patients with esophagogastric (P = 0.002), pancreatic (P = 0.0005), and lung cancer (P = 0.01), whereas in breast cancer patients, high CXCL12 expression conferred an overall survival advantage (P < 0.001)." (PMID 32641130, 2020). "Hence, the leptin and CXCL12 activated miR-218/Wnt loop fuels Wnt signaling to enhance expression of metastatic and osteomimetic genes in aggressive breast cancer cells that home to bone." (PMID 33123472, 2020). "The CXCL12/CXCR4 axis compromises adjuvant therapy in breast cancer." (PMID 32079335, 2020). "In this review, we explore the role of the CXCL12/CXCR4 pathway in breast cancer." (PMID 33096815, 2020). "The CXCL12 axis has been identified to induce proliferation of cell lines derived from many types of cancers, including prostate cancer, breast cancer, lung cancer, multiple myeloma, and pancreatic cancer." (PMID 33363463, 2020). "This study showed that E5 was capable of inhibiting the interaction between 4T1 breast cancer cells and stromal cells mediated by CXCL12, leading to a reduction in migration and adhesion and enhancing the sensitivity of these cells to chemotherapeutics both in vitro and in vivo." (PMID 33006013, 2020). "Other studies found similar results on the effect of CXCL12 on endothelium in breast cancer." (PMID 33096815, 2020). "Finally, the CXCL12/CXCR4 signaling induces breast cancer cell motility and is involved in all types of breast cancer metastasis." (PMID 33096815, 2020). "Moreover, CXCR4, one of the receptor of CXCL12, is a poor prognosis factor in breast cancer patients, independently of ER status, and its high expression has been shown to promote estrogen-independent tumor growth in vivo." (PMID 32727083, 2020). "This suggests that peptides imitating CXCL12-CXCL4 interactions might be a novel therapeutic strategy to prevent CXCL12-induced breast cancer cell migration." (PMID 33096815, 2020). "They promote breast cancer brain metastasis via CXCL12 secretion." (PMID 33096815, 2020). "Moreover, co-expression boosts the CXCL12-induced cell migration in metastatic breast cancer cells MDA-MDB-231." (PMID 33096815, 2020). "Furthermore, the CXCL12 signaling in endothelial cells increases their permeability and enhances migration of breast cancer cells across the blood brain barrier." (PMID 33096815, 2020). "Upregulation of CXCL12 promoted breast cancer cell dissemination and growth in the skeleton." (PMID 32092997, 2020). "In addition, POU domain class 2 transcription factor 1 (known as POU1F1 (Pit-1)) induces the expression of both CXCR4 and CXCL12 in breast cancer cells." (PMID 33096815, 2020). "Increased levels of AQP3 channels, mediating H2O2 transport and inducing CXCL12- cell signaling and migration, could promote breast cancer metastasis." (PMID 32679804, 2020). "However, we reported that CXCL12 expression was significantly increased in the lung of the mouse breast cancer model, which recruited a large number of CD62Ldim neutrophils through the CXCR4/CXCL12 axis." (PMID 33178575, 2020). "Similarly, low molecular weight heparin (LMWH)-taurocholate conjugated with tetrameric deoxycholic acid, namely LHTD4, inhibits TGF-β1 and CXCL12 mediated migration and invasion of breast cancer cells." (PMID 33096815, 2020). "Since the CXCL12/CXCR4 cascade plays important roles in many aspects of breast cancer tumorigenesis, treatments aiming to inhibit this pathway might provide valuable therapeutic tools." (PMID 33096815, 2020). "CAFs in human breast cancer biopsies were shown to be rich in HSF1, and the depletion of HSF1 led to a loss of the factors transforming growth factor-β (TGF-β) and CXCL12/SDF1 known to program the tumor microenvironment in a pro-tumorigenic and metastatic manner." (PMID 32331382, 2020).
breast carcinoma (continued). "Moreover, HIF signaling in osteoblast-lineage cells promotes breast cancer cells growth and dissemination in remote tissues such as lungs via increase in blood levels of CXCL12." (PMID 33096815, 2020). "Moreover, in an autocrine manner through the miR-200s/miR221/DNMT3B regulatory pathway, TGF-β1 maintained the active state of CAFs with a capacity to produce CXCL12, which promoted breast cancer cell proliferation." (PMID 33050237, 2020). "Although CXCL12 signaling seems to exert rather harmful effects on adaptive immunity in breast cancer, one study reported the opposite observations: CXCL12 overexpression in mouse breast cancer cells was found to induce the CD8+ T cells response and to boost the T cell-mediated cytotoxicity." (PMID 33096815, 2020). "In addition, Tregs exposed to hypoxia show increased CXCR4 surface expression which in turn can interact with its ligand stromal-derived-factor-1 (SDF-1 also called CXCL12) to mediate infiltration of Treg cells into breast cancer." (PMID 33262763, 2020). "The present studies indicate that leptin and CXCL12 may upregulate the Wnt/β-catenin pathway in breast cancer." (PMID 33123472, 2020). "Moreover, POU1F1-induced CXCL12 in breast cancer cells promotes recruitment and polarization of macrophages into TAMs." (PMID 33096815, 2020). "Furthermore, CAFs-derived CXCL12 decreases endothelial barrier integrity, enhances vascular permeability and growth of leaky tumor vasculature promoting distant breast cancer metastasis." (PMID 33096815, 2020). "The CXCL12/CXCR4 signaling has also been a therapeutic target in breast cancer research." (PMID 33096815, 2020). "In breast cancer, CXCL12 affects innate immunity via promoting monocytes recruitment into tumors." (PMID 33096815, 2020). "Moreover, CAFs derived from human breast cancer brain metastasis show higher expression of CXCL12 and CXCL16 in comparison with healthy fibroblasts and CAFs from primary breast tumors." (PMID 33096815, 2020). "Similar to previous research, forced CXCL12/CXCR4 signaling in metastatic breast cancers promoted immune system evasion, making it a potential target for inhibiting the resistance of therapeutics to immune checkpoint blockades in metastatic breast cancers patients." (PMID 31815619, 2019). "In addition to the well-known CXCL12/CXCR4 axis in directing the migration of breast cancer cells through the lymphatics, very few studies have been conducted to identify biomarkers associated with the lymph metastasis of breast cancer." (PMID 31443698, 2019). "Similarly, secretion of stromal cell-derived factor 1 (SDF1, also known as C-X-C Motif Chemokine Ligand 12 (CXCL12)) by BMSCs has been implicated in bone metastases of breast cancer cells." (PMID 30993013, 2019). "In addition, CXCL12 was shown to induce angiogenesis by recruiting endothelial progenitor cells (EPCs) in breast cancer, thereby providing sufficient nutrients to fuel tumor growth and metastasis." (PMID 31106200, 2019). "However, the CXCR4/CXCL12 interaction is unlikely involved in the metastasis of breast cancers to the liver." (PMID 31477571, 2019). "Furthermore, after mice bearing breast cancer were treated with antibodies targeting CXCL12, reduced tumor volume and cell number were observed." (PMID 31106200, 2019). "Moreover, CXCL12 expression was found to be higher in breast cancer bone metastasis compared to other sites of metastasis." (PMID 29642534, 2018). "Evidence for a regulatory role of CXCR4/CXCL12 axis in the progression of the metastatic disease was found in breast cancer patients with the organs and tissues with highest CXCL12 expression frequently showing metastases and with CXCL12 working as a chemotactic factor." (PMID 30012106, 2018). "The protein CXCL12 and its receptor CXCR4 has been associated with breast cancer migration." (PMID 30416486, 2018).
breast carcinoma (continued). "Indeed, CXCR4 expression in PT promotes metastasis of CXCR4 positive tumor cells to sites commonly affected by metastatic breast cancer (lymph node, lung, liver, bone marrow and brain) where its ligand CXCL12 is generated in large quantity." (PMID 30012106, 2018). "CXCR4 and CXCL12 expression was analyzed by immunohistochemistry and immunofluorescence on primary tumors (PT), regional and distant metastases of female cats with mammary carcinoma and correlated with serum CXCL12 levels, tumor molecular subtypes and clinicopathological features." (PMID 30012106, 2018). "Previous findings have identified estrogen as a positive regulator of the CXCL12/SDF‐1 gene in breast cancer cells, and we have described that such regulation is part of a positive autocrine feedback loop involving CXCR4 and estrogen receptors to promote cell growth." (PMID 30051594, 2018). "The expression of CXCL12 inhibits the metastasis and growth of primary breast cancer." (PMID 30563570, 2018). "Cytoplasmic CXCL12 immunostaining of primary breast cancer cells was already been showed before and may reflect endogenous CXCL12 being processed just before secretion, as chemokine cell storage is uncommon." (PMID 30012106, 2018). "Moreover, stromal-produced CXCR4/CXCL12 has been suggested to be crucial for priming breast cancer cells to metastasize to the liver." (PMID 30428629, 2018). "Some of the response of breast cancer to CXCR4 may be determined by the presence of estrogen receptors, as the CXCl-12 signalling axis is important for the estrogen-mediated growth of breast cancer cells." (PMID 29098360, 2018). "The receptor CXCR4 and its ligand CXCL12 play crucial roles in breast cancer." (PMID 30012106, 2018). "A similar expression pattern was also observed in breast cancer, where CXCL12 was expressed in tissues commonly affected by breast cancer metastasis including the bone marrow, liver, lung, and lymph nodes, but not other tissues such as the kidney and small intestine." (PMID 29642534, 2018). "More recently, an extensive amount of research has been conducted to clarify the role of CXCR4/CXCL12 axis in human breast cancer and metastatic disease, suggesting that targeted therapies against CXCR4/CXCL12 axis may inhibit tumor growth." (PMID 30012106, 2018). "The interaction between chemokine receptor type 4 (CXCR4) and its cognate ligand stromal-derived factor-1 (SDF1 or CXCL12) plays a crucial role in the regulation of migration and metastasis in a variety of solid tumors including breast cancer (Balkwill, 2004a,b)." (PMID 30564115, 2018). "In order to provide a deeper insight into the role of the CXCR4/CXCL12 axis in FMC, CXCR4 and CXCL12 expression was analyzed and quantified in PT, RM and DM from female cats with mammary carcinoma and its expression was correlated with blood serum CXCL12 levels and molecular subtypes." (PMID 30012106, 2018). "Likewise, blocking the CXCL12/CXCR4 pathway during engraftment of 4T1 mammary carcinoma cells in BALB/c mice yielded similar results (1 in 496 vehicle vs. 1 in 2,466 AMD3100)." (PMID 29632733, 2018). "CAFs were also shown to produce CXCL12 in human breast carcinomas and non-small lung cancer." (PMID 30420856, 2018). "This is illustrated by the finding that AQP3 is required for C-X-C motif chemokine 12 (CXCL12)-induced breast cancer cell signaling and directional migration through a mechanism in which CLCL12-induces the formation of extracellular H2O2 and subsequent internalization." (PMID 30555637, 2018). "Furthermore, expression of CXCR4 and CXCL12 predicts lymph node metastasis in colorectal, esophageal and breast cancer." (PMID 29305742, 2018). "C-X-C chemokine ligand 12 (CXCL12) has important implications in breast cancer (BC) pathogenesis." (PMID 28929029, 2017). "The reasons for this discrepancy are currently unclear but might suggest a difference in the role of CXCL12 in stroma of canine compared to human mammary carcinomas." (PMID 28531107, 2017).